COPB2 (coat protein complex I subunit beta 2)
Diseases named in the same sentence as COPB2 in open-access papers (continued):
Sharing a sentence is not in itself a finding about the gene and the disease.
cancer (continued). "In conclusion, the first pan-cancer analysis of COPB2 indicated that COPB2 expression was significantly correlated with prognosis of cancer patients, genetic alteration, immune cell infiltration, and drug sensitivity in various tumors." (PMID 34676262, 2021). "The present study provides the first pan-cancer analysis for COPB2 using TCGA and the GEO databases." (PMID 34676262, 2021). "Other studies have indicated that COPB2 is involved in the proliferation of cancer cells by disrupting relevant signaling pathways." (PMID 34101128, 2021). "Here, we summarize the emerging roles of coatomer protein COPB2 in cancer development and progression in light of the hallmarks of cancer." (PMID 34101128, 2021). "Understanding the relationship between COPB2 and cancer cell apoptosis provides new strategies for the diagnosis and treatment of cancer and highlights the potential of COPB2 as a new biomarker for the progression of cancer and monitoring treatment effects." (PMID 34101128, 2021). "Because COPB2 is overexpressed in several types of malignant tumors, COPB2 knockdown or silencing would help determine its role in cancer." (PMID 34101128, 2021). "Here, we summarize the current knowledge on the roles of COPB2 in cancer development and progression in the context of the hallmarks of cancer." (PMID 34101128, 2021). "The final scores of COPB2 protein density were 4.8293±1.0932 in cancer tissues and 2.1220±1.0999 in paracancerous tissues (***P<0.001)." (PMID 33211699, 2020). "The results showed that the level of SAG expression correlated positively with the level of COPB2 expression in several human cancer cell lines." (PMID 31926110, 2020). "Recently, the critical role of COPB2 in the tumorigenesis in several human cancers has attracted attention." (PMID 31926110, 2020). "The relationship between COPB2 expression and the overall survival was analyzed by using the clinical data of 194 cancer patients." (PMID 33211699, 2020). "The Oncomine database (one of the main functions of which is gene expression differential analysis) was used to explore the expression of COPB2 mRNA in different cancers, and 189 datasets, including 33 144 samples, were included." (PMID 31710183, 2020). "In our study, the quantitative results indicated that COPB2 had higher expression levels in most cancers compared with normal tissues in the Oncomine database." (PMID 31710183, 2020). "Multiple pathways associated with cancers such as pathways in cancer, PI3K-Akt signaling pathway, and Cytokine-cytokine receptor interaction, were observed to be enriched among LSCC patients with various expression of COPB2 and RYK." (PMID 35715770, 2022). "Additionally, studies on CRC cells have found that COPB2 plays an essential role in cancer cell proliferation and cell cycle progression." (PMID 35909471, 2022). "The level and function of COPB2 across different cancers is controversial." (PMID 35909471, 2022). "COPB2 is also involved in cancer cell apoptosis by targeting downstream microRNAs." (PMID 34101128, 2021). "COPB2 also plays an important role in controlling the invasive ability of cancer cells." (PMID 34101128, 2021). "Several studies have suggested that coatomer protein complex subunit beta 2 (COPB2) may act as an oncogene in various cancer types." (PMID 34676262, 2021). "Therefore, the current study examined COPB2 gene expression in 33 different cancer types based on TCGA, GEO, and CPTAC database data combined with molecular features of gene expression, gene mutation, or protein phosphorylation in a comprehensive manner." (PMID 34676262, 2021). "Whether COPB2 can play an important role in different cancer types via specific mechanisms remains to be studied." (PMID 34676262, 2021). "We also provide insights that can open new avenues for studying the role of COPB2 in cancer." (PMID 34101128, 2021).
cancer (continued). "Therefore, the present study analyzed the potential oncogenic role of COPB2 using TCGA (The Cancer Genome Atlas) and GEO (Gene Expression Omnibus) datasets." (PMID 34676262, 2021). "In the present study, a total of seven algorithms (EPIC, MCPCOUNTER, CIBERSORT, CIBERSORT-ABS, QUANTISEQ, XCELL, and TIDE) was used to explore the underlying association between different levels of immune cell infiltration and COPB2 expression in different cancer types derived from TCGA database." (PMID 34676262, 2021). "COPB2 has been found to be upregulated in all kinds of cancer tissue." (PMID 34101128, 2021). "COPB2 overexpression has been reported in various kinds of cancers." (PMID 34101128, 2021). "Although a mutational hotspot for COPB2 was not identified in the pan-cancer dataset, the highest alteration frequency in the COA region was identified in the 3D model of COPB2." (PMID 34676262, 2021). "Silencing COPB2 greatly affects the apoptotic ability of cancer cells." (PMID 34101128, 2021). "These previous findings indicated that COPB2 might play a critical role in the development of cancer." (PMID 31710183, 2020). "Firstly, the transcript levels of COPB2 in different cancers were analyzed." (PMID 31710183, 2020). "In addition, we collected 41 clinical specimens, and detected the expression of COPB2 in cancer tissues and adjacent tissues by immunohistochemistry." (PMID 33211699, 2020). "Therefore, COPB2 may act as a potential modulator of the TIME in various types of cancers, including cSCC." (PMID 35454945, 2022). "Furthermore, the receptor tyrosine kinase (RTK), c-Jun N-terminal kinase (JNK)/c-Jun signaling pathways, as well as certain microRNAs, such as miR-4461, miR-335-3p, and miR-216a-3p, have been delineated as molecular mechanisms related to the oncogenic functions of COPB2 in cancer progression." (PMID 35454945, 2022). "Here, we observed a correlation between COPB2 transcript levels and immunosuppressive cell types—such as Tregs, neutrophils, and MDSCs —which might exhibit immunosuppressive activities and leading to adverse clinical outcomes in patients with cancer." (PMID 31710183, 2020). "Furthermore, increased COPB2 gene expression has been reported in six human CRC cancer cell lines." (PMID 33211699, 2020). "Ligands inhibiting COPB2 may, therefore, be promising new cancer drugs." (PMID 28415695, 2017). "Based on these three algorithms (EPIC, MCPCOUNTER, and TIDE), the analysis indicated that COPB2 expression and CAF abundance were positively correlated in the majority of the cancer types." (PMID 34676262, 2021). "Concretely, we reveal and confirm that COPB2 is a synthetic lethal partner of KRAS and hence a promising cancer target." (PMID 28415695, 2017). "COPB1 and COPB2, components of the COPI complex, were considered as attractive candidates for further study based on the significant impact in cancer cells on both cell viability and autophagosome formation." (PMID 22745748, 2012). "Reduced expression of COPA, COPB1, COPB2, COPG1, COPD, and COPZ1 induced the punctate GFP-LC3 formation in MDA-MB-231, MDA-MB-468 and SKOV3 cancer cell lines." (PMID 22745748, 2012). "The results demonstrated that the staining of COPB2 in cancer tissues was markedly stronger than that in adjacent noncancerous tissue." (PMID 33211699, 2020). "In addition, we found in this list established cancer genes involved in other types of cancer, such as PDE4DIP, SF3B1, AHNAK, COPB2, CSDE1, KIF5B, NDUFA10, RSRC2." (PMID 31949199, 2020). "Confocal analysis revealed colocalization of GFP-LC3 and LAMP2 in cancer cells treated with siRNA against COPB2, suggesting fusion was not completely blocked by depletion of COPI." (PMID 22745748, 2012). "However, a potential interaction has not been previously reported between COPB2 expression and pan-cancer." (PMID 34676262, 2021).
infection (7 papers, 2012 to 2024). The state of being infected such as from the introduction of a foreign agent such as serum, vaccine, antigenic substance or organism. "First, confirmation of the knockdown of the corresponding genes was achieved using quantitative reverse transcriptase PCR (qRT-PCR) targeting COPA, COPB1, and COPB2, for which mRNA copy numbers in knockdown cells were reduced in all three cases by ≥50% compared to the untreated infection controls." (PMID 32581103, 2020). "This study demonstrates a powerful high-throughput screen for identification of host-virus interactions, identifies multiple host genes associated with HCMV assembly and egress, and uncovers potentially independent functions for coatomer components COPA and COPB2 during infection." (PMID 29946045, 2018). "Studies have shown that the expression of COPB2 in circulating EVs is substantially higher in patients with a mild infection symptom than in patients with a severe infection, suggesting that the expression of COPB2 in circulating EVs may be used as a predictor of disease regression." (PMID 36450704, 2022). "For the three cellular genes with the greatest impact on rHAZV-eGFP expression, namely, COPI coat-like complex components COPA and COPB2 and the adapter-like component COPB1, further validation of their observed impact was performed using infections WT rHAZV." (PMID 32581103, 2020). "Although early stages of infection may be affected by COPA and COPB2 knockdown, this would not account for the substantial loss in infectious virus production." (PMID 29946045, 2018).
COPB2 also shares sentences with these, for which no sentence is quoted: breast tumor (2 papers); adrenocortical carcinoma (1); bile duct cancer (1); cardiomyopathy (1); cervical cancer (1); colorectal adenocarcinoma (1); cortical blindness (1); diffuse large B-cell lymphoma (1); endocervical carcinoma (1); escherichia coli infection (1); juvenile osteoporosis (1); kidney chromophobe (1); larynx squamous cell carcinoma (1); leukemia (1); lymphoid neoplasm (1); lymphoma (1); malignant mesothelioma (1); Micrognathia (1); mitochondrial disease (1); non-small cell lung carcinoma (1); osteoporosis (1); sarcoma (1); short stature, rhizomelic, with microcephaly, micrognathia, and developmental delay (1); skin cutaneous melanoma (1); thymoma (1).